PSPC1 (paraspeckle component 1)
Diseases named in the same sentence as PSPC1 in open-access papers (continued):
Sharing a sentence is not in itself a finding about the gene and the disease.
cancer (18 papers, 2012 to 2026). A tumor composed of atypical neoplastic, often pleomorphic cells that invade other tissues. "The observed dominant negative and lethal phenotypes associated with mutating the polymerization domain of both SFPQ and PSPC1 also indicate an essential role for this function in cancer cell survival." (PMID 40593584, 2025). "Paraspeckle component 1 (PSPC1) is up-regulated and associated with poor survival in cancer patients." (PMID 33478130, 2021). "Paraspeckle protein 1 (PSPC1) overexpression in cancers is known to be the pro-metastatic switch of tumor progression associated with poor prognosis of cancer patients." (PMID 32570949, 2020). "Compared to numerous studies of lncRNA Neat1 participated in tumor progression in multiple cancer types, mechanistic studies for the roles of PSPC1 and the paraspeckle associated proteins in tumor progression is still in the infant stage." (PMID 32570949, 2020). "Recent research indicates that PSPC1 is a new contextual determinant of aberrant subcellular translocation of oncogenes in the growth and metastasis of cancer cells and modulated genes associated with cancer stem cells and EMT." (PMID 36894530, 2023). "Therefore, it motivated us to test the synthetic lethality of PSPC1 inhibition in BRCA1/2-mutated cancer." (PMID 38069409, 2023). "PSPC1 upregulation or PSPC1-Y523F mutation loses nuclear sequestration of tumor suppressive PTK6 to promote cancer EMT, stemness and metastasis via oncogenic cytoplasmic translocation of PTK6 and nuclear translocation of β-catenin, which interacts with PSPC1 to promote Wnt3a autocrine signaling." (PMID 31844057, 2019). "Recent finding identifies the role of PSPC1 as a contextual determinant of subcellular translocation of oncogenes associated with growth, EMT and metastasis of cancer cells." (PMID 41023804, 2025). "PSPC1 (paraspeckle component 1) was recently identified as a contextual determinant of tumor progression in multiple cancer types involving oncogenic reprogramming to switch proapoptotic TGF-β to prometastatic TGF-β via hijacking of Smad2/3 targeting." (PMID 34340703, 2021). "An animal model using multiple cancer cell types showed that PSPC1 correlates with poor survival, potentiating EMT and TGFβ signaling." (PMID 34359789, 2021). "Moreover, elevated wound-healing, migration and invasion ability of cancer cells with CASC19 upregulation were significantly attenuated by PSPC1 siRNA in respect to control cells." (PMID 41023804, 2025). "PSPC1-mediated post-transcriptional gene regulation in cancer, however, remains to be elucidated." (PMID 35681031, 2022). "Our study details the mechanism by which hypoxemia upmodulates the extracellular release of PSPC1 by means of MMP2, such that plasma PSPC1 together with TGFβ activation signaling further promotes tumor metastasis and supports cancer aggressiveness in patients with OSA." (PMID 34359789, 2021). "Indeed, in premalignant cancer cells with low PSPC1 expression, PTK6 is sequestered by its tyrosine-phosphorylated substrate and interacts with PSPC1-phospho-Y523 in the nucleus to suppress the tumorigenic functions of PSPC1." (PMID 34340703, 2021). "Second, upregulation of PSPC1 and IGF1R as well as their downstream signaling are known to activate epithelial to mesenchymal transition (EMT), stemness, and metastasis in association with poor prognosis of cancer patients." (PMID 32570949, 2020). "We speculate that PSPC1 overexpression in tumors could be a potential biomarker for suggestion of cancer patients to receive treatment of IGF1R inhibitor." (PMID 32570949, 2020). "Although previous evidence has shown that PSPC1 is strongly associated with TGFβ expression, this finding in monocytes from patients with OSA provides biological support for the increased tumor risk, cancer aggressiveness, and mortality due to cancer that has been reported in these patients." (PMID 34359789, 2021).
cancer (continued). "Moreover, overexpression of PSPC1 or other paraspeckle proteins may be a potential biomarker for identification of subgroups of cancer patients for treatment with IGF1R inhibitor." (PMID 32570949, 2020). "IH also elevates paraspeckle protein-1 (PSPC1), activating the TGF-β-SMAD pathway, and promoting epithelial-mesenchymal transition (EMT) and cancer stem cell (CSC)-like features." (PMID 39070143, 2024). "For example, PSPC1 activates metastatic reprogramming by increasing TGF-β1 secretion and promotes EMT in cancer cells." (PMID 34650978, 2021). "Our results provide lines of evidence that the PSPC1/IGF1R axis is the critical signaling to facilitate cancer cell motility and potentially as a therapeutic biomarker to predict malignant subtypes of cancer for receiving treatments with IGF1R inhibitor." (PMID 32570949, 2020). "The significant increase of PSPC1 after DNR and MTX treatments points to possible important role of nuclear paraspeckles in anti-cancer activities of anthracycline/anthracenedione drugs." (PMID 23443080, 2012). "In this study, we explored whether IH-mediated PSPC1 overexpression might contribute to the activation of the TGFβ/SMAD pathway, promoting EMT and CSC and explaining the increased cancer aggressiveness in patients with OSA." (PMID 34359789, 2021). "Thus, PSPC1 is the contextual determinant of the oncogenic switch of PTK6/β-catenin subcellular localizations, and PSPC1-CT131 functions as a dual inhibitor of PSPC1 and PTK6 with potential for improving cancer therapy." (PMID 31844057, 2019). "Finally, we show that long term NONO and PSPC1 depletion results in progressive telomere shortening in cancer cells." (PMID 40593584, 2025). "Thus, we propose that PSPC1 activity essentially amplifies critical tumor progression by EMT, which might explain the high cancer aggressiveness in patients with OSA." (PMID 34359789, 2021). "PSPC1 enhances epithelial–mesenchymal transition (EMT), stemness and tumor growth through the activation of core transcription factors (TFs), such as EMT-TFs (e.g., Snail, Slug, and Twist), cancer stem-like cells (CSC)-TFs (e.g., Oct4, Nanog, and Sox2), and c-Myc4." (PMID 31844057, 2019). "Moreover, PSPC1, as a substrate of nuclear PTK6, is the contextual determinant of PTK6 nucleocytoplasmic shuttling and modulates the switch of tumor-suppressive PTK6 in the nucleus of normal or premalignant cells to oncogenic PTK6 in the cytoplasm of malignant cancer cells." (PMID 34340703, 2021).
tumor (13 papers, 2015 to 2025). "PSPC1 is an interaction partner of Smad2/3 as TGF-β1 the contextual determinants of the response will be dichotomous TGF-β1 function changes from tumor inhibition in precancerous cells to metastasis promotion in malignant cells." (PMID 36894530, 2023). "PSPC1 siRNA alone also significantly inhibited the tumor growth, including complete tumor regression in one mouse, compared to control siRNA (p < 0.0001)." (PMID 38069409, 2023). "Combining PSPC1 siRNA with olaparib promoted greater tumor regression than did PSPC1 siRNA alone (p = 0.211), olaparib alone (p < 0.0001), and control siRNA (p < 0.0001)." (PMID 38069409, 2023). "PSPC1 signals were strong in 30 tumor samples, whereas weak in 84 tumor samples and normal mammary tissues." (PMID 35681031, 2022). "Lastly, it is interesting to highlight the synergistic effect when tumor cells are exposed to high concentrations of PSPC1 and TGFβ in the presence of IH." (PMID 34359789, 2021). "Complementarily, our results show that high PSPC1 levels contained in the plasma of patients with OSA maintain a paracrine effect when exposed to tumor cells, inducing the overexpression of certain EMT transcription factors such as TWIST and SLUG." (PMID 34359789, 2021). "In tumor cells, PSPC1 interacts with SMAD2/3 in the nucleus through its NOPS-coil domain in a TGFβ-dependent manner." (PMID 34359789, 2021). "PSPC1 protein expression is accompanied by enhanced TGFβ, which ultimately switches from the immune surveillance role to the tumor progression function." (PMID 34359789, 2021). "PTK6 was identified via its interaction with PSPC1 in the nucleus by proteomic analysis and acts as a tumor suppressor to abrogate the oncogenic effects of PSPC1." (PMID 34340703, 2021). "PSPC1 is known to act as an pro-metastatic driver in HCC4, whereas nuclear PTK6 is implicated in tumor suppression." (PMID 31844057, 2019). "Together, our results demonstrated that the synergized PSPC1/PTK6/β-catenin axis regulates tumor migratory ability and malignant phenotype leading to tumor growth and metastasis in a mouse orthotopic HCC model." (PMID 31844057, 2019). "In contrast, these tumor progression signatures were significantly downregulated in PSPC1/PTK6- and PSPC1-CT131-treated HCC cells." (PMID 31844057, 2019). "PSPC1 is also the interacting partner of Smad2/3 acting as a contextual determinant of TGF-β1 responses to switch the dichotomous TGF-β1 function from tumor suppressing in precancerous cells to pro-metastatic signaling in malignant cancer cells." (PMID 31844057, 2019). "Collectively, our results suggested that the dynamic interaction of PSPC1 or PSPC1-Y523F with PTK6 or β-catenin modulated autocrine Wnt3a/β-catenin signaling to synergize tumor progression in HCC." (PMID 31844057, 2019). "Together, our data suggest that nuclear PTK6 forms a complex with tyrosine-phosphorylated PSPC1, which suppresses the tumor progression effects of PSPC1." (PMID 31844057, 2019). "Similarly, in our present study, we have established that high CASC19 expression increases PSPC1 protein availability in the nucleus which promotes nuclear retention of β-catenin leading to tumor progression." (PMID 41023804, 2025). "Notably, we revealed the potential interaction between CASC19 and a metastatic reprogramming protein PSPC1 (paraspeckle component 1), which is known to be involved in the nucleocytoplasmic shuttling of oncoproteins like β-catenin to promote tumor progression." (PMID 41023804, 2025). "The potential contribution of hypoxia to PSPC1 expression could be relevant in tumor cells, given that hypoxia is a common characteristic of the tumor microenvironment." (PMID 34359789, 2021). "Although it has been proposed that PSPC1 upregulation in tumor cells could be due to cellular stress, its mechanism has not been completely clarified." (PMID 34359789, 2021).
tumor (continued). "Our finding of PSPC1 as a substrate that sequesters PTK6 tyrosine kinase in the nucleus provides an additional example for the crucial role of tyrosine phosphorylation of PTK6 nuclear substrates in tumor suppression." (PMID 31844057, 2019). "Taken together, our IHC results on HCC tissues demonstrated that decreased expression of p-Y523 PSPC1 as a marker for tumor progression might be used as an index of therapeutic intervention to improve the survival of HCC patients." (PMID 31844057, 2019). "The ability of PSPC1-Y523F to revert the tumor suppressive function of the PTK6/PSPC1 axis raised a hypothesis that this mutant might promote the shuttling of PTK6 from nucleus to cytoplasm." (PMID 31844057, 2019). "However, the TGFβ induction mediated by PSPC1 suggests that OSA could also affect the intrinsic properties of eventual tumor cells promoting their aggressiveness." (PMID 34359789, 2021). "However, it should also be noted that PSPC1 can promote tumor aggressiveness in other ways." (PMID 34359789, 2021). "We found that the tumor progression gene signatures associated with metastasis, stemness, and the C-Myc, TGF-β1, Wnt/β-catenin, and PTK6 oncogenic pathways were significantly upregulated in cells expressing the PSPC1, PSPC1-Y523F, and PSPC1-Y523F/PTK6 constructs." (PMID 31844057, 2019). "We further identify PSPC1-CT131 as an inhibitor to abrogate the oncogenic functions of PSPC1 and PTK6 and to interfere with oncogenic translocations of PTK6 and β-catenin, thus suppressing tumor progression in HCC models." (PMID 31844057, 2019). "In contrast, a decrease in the expression of p-Y523-PSPC1 is a warning of the synergistic oncogenic activation of PSPC1, nuclear β-catenin and cytoplasmic PTK6 that facilitates tumor progression in HCC patients." (PMID 31844057, 2019). "We thus tested this synergism in tumor promotion by coexpression of PTK6 and PSPC1-Y523F in SK-hep1 cells or by expressing PSPC1 or PSPC-1-Y523F in PTK6 highly expressed SNU-387 cells." (PMID 31844057, 2019). "To dissect the functional consequences of PSPC1 phosphorylation by PTK6, we expressed the phosphorylation-defective mutant PSPC1-Y523F to test its effect on the tumor suppressive functions of the PTK6/PSPC1 axis, and PSPC1-Y383F was included as a control." (PMID 31844057, 2019). "PSPC1 also facilitates the cytoplasmic translocation of protein tyrosine kinase 6 (PTK6) to become an oncogene, and β-catenin nuclear translocation to interact with PSPC1 for augmenting Wnt3a autocrine signaling and tumor progression." (PMID 34359789, 2021). "An innovative dual inhibitor derived from a unique C-terminal polypeptide composed of 131 amino acids of PSPC1 targeting both oncogenic PSPC1 and PTK6 nucleocytoplasmic shuttling was shown to exhibit synergistic tumor-suppressive effects in HCC cell lines and mouse models." (PMID 34340703, 2021). "PSPC1 is a master activator of EMT-TFs, increases TGF-β1 secretion to amplify aTGF-β1 signaling, and controls the pro-metastatic switch of TGF-β1 from a tumor suppressor to a tumor promoter." (PMID 33478130, 2021). "First, our results demonstrated that PSPC1 is the upstream modulator of IGF1R expression to activate downstream FAK/Src focal adhesion signaling and facilitate cell motility that is crucial for tumor progression." (PMID 32570949, 2020). "Our results indicated that PSPC1-Y523F expression shifts the preference of its nuclear partner from PTK6 to β-catenin, which likely contributes to the functional synergism between PSPC1 and cytoplasmic PTK6 in tumor promotion." (PMID 31844057, 2019). "In brief, METTL3-modificatory m6A regulates the interaction of PANC754 with PSPC1 and H3K4me1 to form ncRNA/RBP/histone repression complex at gene promoter region to mediate the “Don’t eat me” LGALS7 signaling pathway, thereby exerting tumor-suppressing effects against CRC." (PMID 40634299, 2025).
tumor (continued). "Therefore, PSPC1 is the contextual determinant for the reciprocal oncogenic subcellular translocation of cytoplasmic PTK6 and nuclear β-catenin to exert synergistic effects on oncogenic tumor progression." (PMID 34340703, 2021). "We selected 30 tumor progression-enriched gene signatures downstream of PSPC1 and PTK6 signaling pathways to demonstrate the significant up-regulation (in red) and down-regulation (in green) of gene expression under PSPC1/PTK6 dynamic interaction and PSPC1-CT131 treatment." (PMID 31844057, 2019). "In contrast, PTK6 could not suppress PSPC1-Y523F-induced tumor formation and metastasis and even enhanced these effects." (PMID 31844057, 2019).
infection (4 papers, 2018 to 2025). The state of being infected such as from the introduction of a foreign agent such as serum, vaccine, antigenic substance or organism. "First, we designed shRNAs (sh2 and sh3) targeting PSPC1 and established stable knockdown cell lines by lentiviral infection." (PMID 40959076, 2025). "The first significant finding of this research is the relocalization of PSPC1 to the cytoplasm upon HCV-JFH1 infection." (PMID 38793620, 2024). "Overall, the findings presented in this research shed light on the complex interplay between PSPC1 and HCV during infection." (PMID 38793620, 2024).
genetic diseases (1 paper, 2025). "Additionally, ClinVar lists an R327C mutation of unknown significance in PSPC1 associated with inborn genetic diseases." (PMID 39698821, 2025).
PSPC1 also shares sentences with these, for which no sentence is quoted: leukaemia (2 papers); liver cancer (2); lung carcinoma (2); nasopharyngeal carcinoma (2); tauopathies (2); Breast (1); intellectual disabilities (1); preeclampsia (1); ptosis (1); Sleep apnea (1).